EGFR (epidermal growth factor receptor)
Diseases named in the same sentence as EGFR in open-access papers (continued):
Sharing a sentence is not in itself a finding about the gene and the disease.
tumor (continued). "Successful retargeting has been demonstrated against a range of tumor-associated receptors, including IL13Rα2, uPAR, GFRα1, HER2, EGFR, PSMA, and EGFRvIII, enabling selective infection of various cancer cell types." (PMID 41403403, 2026). "We integrated mouse PK with in vitro/in vivo PD data to build a mechanistic Quantitative System Pharmacology (QSP)-PK-PD model linking drug disposition to folate biology, Epidermal Growth Factor Receptor (EGFR) signaling, and tumor growth inhibition." (PMID 42076061, 2026). "Given this, it would be interesting to compare CSPG4 levels in EGFR mutant tumours and their released EVs with samples from EGFR‐TKI treatment‐naïve patients at baseline and upon progression." (PMID 41581122, 2026). "PLK1 mRNA expression was markedly elevated in the tumor tissues versus adjacent normal tissues from EGFR-mutant NSCLC patients." (PMID 41539998, 2026). "Human epidermal growth factor receptor, hormone receptors, and angiogenesis factors are among the established therapies in tumor reduction and managing side effects." (PMID 41613789, 2026). "We delineate a central carcinogenic spine encompassing lung epithelial injury, chronic inflammation, growth factor signaling activation-particularly epidermal growth factor receptor (EGFR) pathways-and tumor microenvironment remodeling." (PMID 41595186, 2026). "In a xenograft mouse model, EGFR-tEVs + Dox administration resulted in a 33.1% reduction in tumor volume and an 82.8% decrease in Ki-67 expression compared to the control group." (PMID 42074332, 2026). "Conversely, VPS18 has also been shown to suppress EGFR expression and lung tumorigenesis, suggesting a context-dependent tumor-suppressive function through modulation of growth factor receptor pathways." (PMID 41516402, 2026). "Considering the established link between EMT, tumor metastasis, and poor prognosis in EGFR-mutant NSCLC, we investigated the effects of PLK1 inhibitors combined with osimertinib on the migratory properties of resistant cells." (PMID 41539998, 2026). "In vivo tumorigenesis of nude mice revealed that EGFR-001 overexpression significantly increased tumor volume and weight compared with EGFR-004 overexpression." (PMID 41540015, 2026). "By comparing pEGFR-binding molecules, we found that an uncharacterized lncRNA, EUDAL, was highly enriched in hypoxic tumor cells with constitutive and high EGFR activation." (PMID 40940319, 2025). "Preclinical studies have confirmed that when the EGFR pathway is inhibited, tumor cells can become dependent on VEGF signaling for survival and proliferation." (PMID 41158851, 2025). "EGFR-target therapy (cetuximab and panitumumab) and small-molecule TKIs have been reported to inhibit tumor growth and disease progression, which demonstrate the promising therapeutic option in CRC patients." (PMID 40959565, 2025). "Emerging evidence suggests that EGFR signaling not only drives tumor progression, but also influences the release and cargo composition of extracellular vesicles (EVs), which play a key role in intercellular communication within the tumor microenvironment." (PMID 40210802, 2025). "The most common mechanisms of resistance to anti-EGFR therapy are mutations in RAS genes, secondary mutations in BRAF, EGFR or HER2 genes, and also tumor heterogeneity." (PMID 40002260, 2025). "These components establish a positive feedback loop that accelerates tumor progression and reinforces oncogenic signaling through EGFR-dependent pathways." (PMID 40725192, 2025). "Recent mechanistic insights reveal that coagulation system activation is not merely a bystander phenomenon but actively contributes to tumor progression through EGFR signaling modulation." (PMID 41018085, 2025).
tumor (continued). "In NCI-H23 cells, these anti-EGFR-LaB6 NCs demonstrated strong absorption, effectively alleviating tumor hypoxia." (PMID 39897552, 2025). "In recent years, novel EGFR detection methodologies have emerged, exemplified by liquid biopsy platforms incorporating circulating tumor cells (CTCs), circulating tumor DNA (ctDNA), and exosomes." (PMID 41244899, 2025). "This study used a confocal laser scanning microscope (CLSM) to target tumor-induced cells in hamster mucosal tissue by conjugating GNPs with Anti-EGFR and then labeling them with FITC." (PMID 41367681, 2025). "For instance, exosomes functionalized with anti-EGFR nanobodies demonstrated enhanced uptake by EGFR-expressing tumor cells." (PMID 40284522, 2025). "All of these mechanisms of action translated into excellent tumor growth inhibition effects in vivo, as observed in a panel of NSCLC xenograft models with diverse receptor density and EGFR and kRAS mutation status." (PMID 40452841, 2025). "The CAR-T cells showed the ability to kill EGFR-overexpressing B16 tumor cells at different E:T ratio in vitro." (PMID 40122855, 2025). "Together, these results demonstrate DNAJC10 overexpression inhibits GBM progression across different EGFR genetic backgrounds, highlighting its robust in vivo tumor-suppressive activity." (PMID 41191192, 2025). "In one study, EGFRvIII-targeting CAR T cells have been engineered to secrete TEAMs against wild-type EGFR, as antigen loss in tumors treated with EGFRvIII CAR alone is correlated with tumor persistence and amplification of wild-type EGFR." (PMID 40867165, 2025). "Nevertheless, cetuximab remains an important tumor-targeting antibody because EGFR overexpression is common in NSCLC49." (PMID 41219228, 2025). "Despite distinct oncogenic drivers (e.g., histone mutations in children vs. IDH mutations or EGFR amplifications in adults), both harbor OPC‐like compartments, underscoring a shared tumor‐promoting potential within the glial lineage." (PMID 41036308, 2025). "Amplifications and mutations in RTKs, such as EGFR, PDGFR, and fibroblast growth factor receptors, lead to dysregulated signaling, promoting tumor proliferation and survival." (PMID 40628732, 2025). "Glycine and serine metabolism are frequently upregulated, especially in tumors with EGFR and Phosphoserine Phosphatase (PSPH) mutations, sustaining tumor growth, migration, and immune evasion." (PMID 40775789, 2025). "In this study, we present novel evidence demonstrating that EPN3 affects tumour progression through interacting with EGFR and inhibiting the lysosomal degradation pathway of EGFR." (PMID 39910656, 2025). "The amplification of the EGFR gene (epidermal growth factor receptor), its upregulation, and increased protein expression can be used to predict tumor progression significantly." (PMID 40028480, 2025). "Next, we evaluated the effect of the intralesional administration of rTBL-1 on the development of established EGFR− ectopic tumor allografts in immunocompetent syngeneic rodents." (PMID 40006027, 2025). "EGFR mutant tumours deviate from their baseline copy number state significantly more than EGFR wild-type tumours (FDR = 7.4×10−5)." (PMID 41509216, 2025). "These alterations allow tumor cells to bypass the EGFR signaling pathway, thereby enhancing their resistance to TKIs." (PMID 40003951, 2025). "miR-7 and miR-125 typically function as tumor suppressors by targeting EGFR or HER2/3, respectively, or their downstream signaling components." (PMID 41154417, 2025).
tumor (continued). "In human colorectal adenocarcinoma (HT29), it effectively inhibits the phosphorylation of EGFR and its downstream signaling pathways, thereby suppressing tumor cell growth and survival mechanisms." (PMID 40728967, 2025). "This case underscores the potential efficacy of EGFR TKIs and anti-angiogenic agents in inducing unique tumor microenvironment modifications, while highlighting the transient nature of such responses and the critical need to address resistance mechanisms." (PMID 40428273, 2025). "For example, bispecific ADCs that target both HER2 and EGFR have shown promising results in preclinical models by increasing the breadth of tumor targeting." (PMID 41184856, 2025). "We observed enhanced TAVO412 anti-tumor effects when tumors were treated in combination with EGFR-TKIs in several in vivo models." (PMID 40452841, 2025). "This suggests that the PCZ‐loaded hydrogel exerted a sustained inhibitory effect on EGFR endocytosis within the tumor foci." (PMID 39560161, 2025). "By sustaining parallel pathways despite EGFR blockade, these stromal interactions highlight the importance of considering the tumor microenvironment as a therapeutic target." (PMID 40940901, 2025). "Experimental models showed that genetic disruption or inhibition of EGFR or ADAM17effectively blocked KRAS-induced PDAC tumour growth in vivo." (PMID 40427200, 2025). "Another protein, known as exosomal annexin A6 (AnxA6), has been found to be highly expressed in gemcitabine‐resistant TNBC cells and induces tumour resistance through the inhibition of EGFR ubiquitination and degradation." (PMID 40032646, 2025). "Overall, tarloxotinib-E demonstrated a marked anti-tumor effect with lower systemic toxicity compared to other EGFR and HER2-targeted therapies." (PMID 40710312, 2025). "Conventional biomarkers, such as carcinoembryonic antigen (CEA), epithelial cell adhesion molecules (EPCAM), and EGFR, can be found in lung tissue, tumor-draining pulmonary blood, and bone marrow samples used for diagnosing NSCLC." (PMID 40176898, 2025). "Initial findings revealed issues like limited CAR-T cell persistence in the tumor microenvironment and on-target/off-tumor toxicity as a result of EGFR expression in normal tissues." (PMID 40312353, 2025). "Although CAR T cells are compelling preclinically, translation is limited by individualized manufacturing, on-target/off-tumor toxicities (e.g., with epidermal growth factor receptor (EGFR)-directed products), and premature T-cell exhaustion." (PMID 41209565, 2025). "In summary, CMTM4 prevents EGFR from lysosomal degradation, which further amplifies EGFR signaling and activation of the Akt/mTOR/NF-κB pathways to promote tumor growth." (PMID 39948411, 2025). "On theother hand, the anti-tumor effect of doxorubicin is mediated by thereorganization of lipid rafts via the EGFR/ Src signaling." (PMID 40264586, 2025). "Some AI studies have attempted to predict the EGFR status of a tumor based on certain radiomic features from chest CT, obtaining AUC values around 0.765." (PMID 40075729, 2025). "First, Spearman correlation was performed to analyze the relationship between EGFR-related genes and EGFR scores in malignant tumor cells across 34 scRNA-Seq datasets." (PMID 40574864, 2025). "The epidermal growth factor receptor (EGFR) pathway plays a pivotal role in tumor proliferation, survival, and therapy evasion." (PMID 41156200, 2025). "For instance, EGFR amplifications activate PI3K/AKT signaling to fuel tumor growth, while CDK4 gains bypass cell cycle checkpoints, and RB1 losses impair homologous recombination repair." (PMID 40636690, 2025). "Conversely, miR‐146a‐5p functions as a tumor suppressor in PCa; after androgen deprivation therapy, its downregulation in CAFs reduces EGFR mRNA degradation, thereby weakening its tumor‐suppressive function and facilitating metastasis." (PMID 40761481, 2025).
tumor (continued). "In contrast, EGFR expression remained elevated in normal tissues, with a non-significant increase in tumors (p = 0.929), suggesting limited tumor-specific imaging potential." (PMID 40563608, 2025). "Recent studies have also explored the role of EGFR in the tumor microenvironment and immune evasion, opening avenues for combination therapies with immune checkpoint inhibitors." (PMID 40728967, 2025). "Epidermal growth factor receptor (EGFR) signaling plays a key role in tumor progression and radioresistance." (PMID 40244089, 2025). "FBXW7 loss-of-function produces complex, context-dependent effects: it can promote tumor aggressiveness by stabilizing oncogenic substrates (e.g., Cyclin E, EGFR) yet also generate pharmacologically exploitable vulnerabilities." (PMID 41373479, 2025). "In vivo studies confirmed that EGFR-scFv modification significantly enhanced tumor targeting and prolonged the retention of ExoscFv within the TME." (PMID 40733107, 2025). "EGFR also affects the expression of some immunosuppressive molecules in tumor cells, among which the most studied is PD‐L1." (PMID 40859900, 2025). "For instance, the anti-epidermal growth factor receptor (EGFR) mAb cetuximab inhibits EGFR signalling, which can indirectly enhance the efficacy of DNA-damaging platinum drugs and improve their anti-tumour activity." (PMID 40518502, 2025). "TERT promoter mutations increase telomerase activity, allowing for indefinite tumor cell replication, while EGFR amplifications lead to continuous activation of intracellular signaling pathways that promote cell proliferation." (PMID 41567539, 2025). "These reproducible results prompted us to ask why tumor cells exhibit different responses to hypoxia-induced EGFR activation." (PMID 40940319, 2025). "Using lncRNA-seq, a novel exosomal long noncoding RNA (lncRNA), lnc-MLETA1 was found to promote tumor metastasis by regulating the miR-186-5p/EGFR and miR-497-5p/IGF1R axes in NSCLC." (PMID 40165954, 2025). "EGFR is a well-established therapeutic target in oncology, as its dysregulation drives tumor proliferation, survival, and metastasis across various cancer types." (PMID 40906750, 2025). "Amivantamab is a humanized EGFR-cMET BsAb that has shown a managed safety profile and broad-spectrum anti-tumor efficacy in patients with EGFR exon 20 insertion, EGFR C797S mutation, MET amplification, or resistance to third-generation EGFR TKI Osimertinib." (PMID 40057807, 2025). "Analysis of clinical samples from HCC patients revealed increased expression of both STARD4 and EGFR in tumor tissues, with a strong correlation between STARD4 expression and malignancy progression." (PMID 40831538, 2025). "This silencing is significant because ADAMTS8 plays a role in inhibiting tumor cell growth and motility by antagonizing the EGFR-MEK-ERK signaling pathway, which is crucial for cancer cell proliferation and survival." (PMID 40650042, 2025). "Amivantamab is a BsAb that targets both EGFR and cMET on tumor cells and it already has several FDA approvals." (PMID 40565299, 2025). "In the in vitro assessments, FH-EB02, which has a weaker anti-EGFR and a more potent anti-B7H3 arm, demonstrated a greater binding capacity with tumor cells, higher selectivity for B7H3/EGFR coexpressing tumor cells, as well as prominent ADCC effect." (PMID 41291854, 2025). "We further demonstrated that the endocytosis inhibitor PCZ effectively inhibited both EGFR and EGFR‐cetuximab complexes, dramatically increasing the tumor cell‐killing efficacy by enhancing the ADCC effect." (PMID 39560161, 2025). "Lastly, LUSC tumours showed upregulation of protein kinases such as EGFR, SRC and MAPK14, and EGFR phosphorylation correlated with ligand abundance rather than with gene amplification." (PMID 40849356, 2025). "Next, we compared the significance of early tumor shrinkage between patients treated with chemotherapy plus an anti-EGFR antibody and patients treated with chemotherapy plus bevacizumab." (PMID 40280867, 2025).
tumor (continued). "Epidermal growth factor receptor (EGFR) mutations are common in patients with advanced NSCLC and are recognized as critical oncogenic drivers of tumor growth and progression." (PMID 40075700, 2025). "Distribution of age, EGFR and Ki-67 labelling index expressed strong positive (≥0.5) correlation with the grade of tumours." (PMID 40227788, 2025). "Within the TME, EGFR inhibits anti‐tumour immune cells and recruits' immunosuppressive cells through inducing the expression of cytokines, chemokines, and other effector proteins." (PMID 40830825, 2025). "The PI3K/AKT signaling is the key downstream pathway of EGFR which regulates tumor cell growth and apoptosis resistance to chemotherapy, as well as cell invasion and migration." (PMID 40831538, 2025). "EGFR expression in immune cells profoundly influences their functions and tumor microenvironment dynamics." (PMID 40859900, 2025). "An EGFR‐Vδ2 bispecific T‐cell engagers (bsTCE) were developed to activate Vγ9Vδ2 T cells and selectively kill EGFR‐overexpressing tumor cells, which promoted the downstream activation of CD4+, CD8+ T cells and NK cells, but not Tregs." (PMID 40859900, 2025). "Univariate Cox analysis revealed that EGFR mutation type, TKI treatment response prior to TRTinitiation, BED of TRT, and tumor status at the time of TRT initiation were significantly related to PFS." (PMID 41383503, 2025). "We further demonstrate that RICTOR regulates the synthesis of GD3 gangliosides through ZFX and UGCG, and triggers the activation of the EGFR signaling pathway, thereby promoting tumor growth." (PMID 40934285, 2025). "This is of significant clinical importance as inadequate tumor content is a major contributing factor to genomic EGFR test failures." (PMID 41211715, 2025). "This tumor-selective binding enabled Depatux-M to avoid the typical skin and gastrointestinal toxicities seen with conventional EGFR inhibitors." (PMID 40918539, 2025). "Hypoxic conditions within the tumor microenvironment also induce GPER upregulation via HIF-1α in an EGFR/ERK dependent manner." (PMID 40641933, 2025). "HNSCC is among the many cancers where EGFR is overexpressed, playing a pivotal role in tumor growth and progression." (PMID 40296914, 2025). "Recent studies in mouse tumor models have shown that LPS promotes angiogenesis within tumor tissues by modulating the EGFR/IL8 and VEGFR/STAT3 signaling pathways, thereby enhancing tumor growth, proliferation, and metastasis." (PMID 40458800, 2025). "In-vitro studies suggested that lapatinib (an EGFR-inhibitor) reduce corticotroph tumor cell proliferation." (PMID 40064752, 2025). "Compared with NK cells transduced with an empty vector, ready‐to‐use EGFR‐CAR NK cells demonstrated enhanced tumor cell killing capabilities." (PMID 40859900, 2025). "Starting from the epidermal growth factor receptor (EGFR) as the first discovered tumor therapeutic target, the search for potential molecules as targeted therapeutic targets has been a hot research topic." (PMID 40672756, 2025). "EGFR, a key tyrosine kinase receptor, regulates critical growth factors involved in tumor proliferation and survival." (PMID 40628732, 2025). "Molecular profiling of the tumor tissue revealed an EGFR exon 19 deletion (19del) and T790M-negative NSCLC." (PMID 41158851, 2025). "Most of the 313 new disease links belonged to the DisGeNET class neoplasms (n = 40; EGFR, ERBB2, KITLG, AREG) but also to immune diseases (n = 29; FAS), neurological diseases (n = 13; PNPLA6), and cardiovascular diseases (n = 13; CD163)." (PMID 40593564, 2025). "HER3 lacks kinase activity but plays pivotal roles such as cell proliferation, physiological homeostasis, and tumor development by forming a heterodimer with human epidermal growth factor receptor 2 (HER2) or EGFR." (PMID 40065768, 2025).